ROS1 (ROS proto-oncogene 1, receptor tyrosine kinase)
Diseases named in the same sentence as ROS1 in open-access papers (continued):
Sharing a sentence is not in itself a finding about the gene and the disease.
glioma (42 papers, 2017 to 2026). A benign or malignant brain and spinal cord tumor that arises from glial cells (astrocytes, oligodendrocytes, ependymal cells). "Mutations in genes including ROS1, ALK, NF1, KRAS, MEK, and CRAF have been identified across glioma subtypes, highlighting the necessity for molecular classification beyond traditional histopathology." (PMID 41514664, 2026). "While ALK gene fusions occur in both low-grade and high-grade gliomas, NTRK/ROS1/MET fusions show a stronger association with high-grade tumors." (PMID 40853542, 2025). "In pediatric gliomas and glioneuronal tumors, the ROS1 fusion, resulting from microdeletions at 6q22, has been identified as an oncogenic driver, highlighting the significance of ROS1 fusions in pediatric tumors." (PMID 41275415, 2025). "These drugs are FDA- and EMA-approved for NSCLC treatment, but there are just a few case reports mentioning good response to entrectinib in ROS1-fused glioma." (PMID 39409964, 2024). "The CEP85L-ROS1 fusion pattern is one of many fusion genes that can be formed with the ROS1 proto-oncogene but has itself only been reported in a case of glioma." (PMID 36923435, 2023). "Similar results were obtained in the U343MG human glioma cell line, in which endogenous ROS1 expression and activation were undetectable." (PMID 38201436, 2023). "From these results, an enhanced oncogenic function of the KLC1-ROS1 fusion in glioma cells compared to wild-type ROS1, especially under serum factor-deprived conditions, can be suggested." (PMID 38201436, 2023). "In 2019, the first international joint study focusing on fusion genes of infantile gliomas reported that almost all ROS1 or NTRK fusion genes were found in hemispheric primary tumors, and over 80% of these genes were found in malignant tumors." (PMID 37372381, 2023). "Our study clarified the detailed oncogenic molecular machinery induced by KLC1-ROS1, a novel ROS1 fusion gene discovered in a glioma case." (PMID 38201436, 2023). "When wild-type ROS1 and KLC1-ROS1 fusions were expressed in human glioma cell lines, immunoblotting revealed that KLC1-ROS1 fusion specifically activated the JAK2–STAT3 axis compared with wild-type ROS1." (PMID 38201436, 2023). "GOPC, a protein that containing a coiled helix motif, is also one of the prognostic markers of Early-Stage Lung Squamous Cell Carcinoma, and when fused with ROS1 and other ROS1, it can represent a rare but recurrent drug target in various glioma types." (PMID 35859893, 2022). "A potential mechanism involved in spontaneous differentiation of gliomas harboring ALK/ROS1/NTRK/MET alterations is oncogene-induced senescence." (PMID 34704035, 2021). "Although ROS1 fusion in glioma is quite rare, several reports have highlighted it as a targetable genetic alteration." (PMID 33673070, 2021). "The data shown in our study indicate that overexpressed JMJD1C increases the expression of M1 markers (IL‐1β, TNF, CXCL9, IL‐23, ROS1, IL‐12a, and IL‐12b) both in the glioma mouse models and in the CD14+ monocytes co‐cultured with glioma cells." (PMID 34586733, 2021). "Although GOPC-ROS1 represents the most common ROS1 alteration in gliomas, CEP85L–ROS1, ZCCHC8-ROS1, and KLC1-ROS1 have also been reported." (PMID 32164789, 2020). "Our comprehensive study, including clinical experience and in vitro data on therapy of NTRK/ROS1-fusion-positive pediatric high-grade gliomas, provides first insights into potential effective combination therapies." (PMID 33353026, 2020). "Notably, NTRK- and ALK-driven tumors formed a cluster separate from MET- and ROS1-driven gliomas, indicating systematic differences between these two groups with similar oncokinases." (PMID 41381884, 2026).
glioma (continued). "Some of these gliomas feature alterations in genes such as ROS1, ALK, MET, and NTRK1–3." (PMID 41155159, 2025). "Different ROS1 inhibitors can potentially play a therapeutic role in ROS1-fused glioma." (PMID 39409964, 2024). "In connection with this hypothesis, it could be advocated that gliomas with such ROS1 fusions may be treated by drugs that target a pathway other than ROS1 activity." (PMID 38201436, 2023). "Finally, to confirm the therapeutic efficacy of targeting the ROS1–JAK–STAT axis in KLC1-ROS1 fusion-harboring gliomas, the antitumor efficacies of lorlatinib, ruxolitinib, and the Mcl-1 inhibitor subtoclax, in combination with TMZ, were investigated." (PMID 38201436, 2023). "In addition, only a slight increase in the activation of KLC1-ROS1 fusion was confirmed compared with that of wild-type ROS1 in both glioma cell lines." (PMID 38201436, 2023). "Beyond these, in adult gliomas, the main partner of ROS1 fusions is GOPC." (PMID 37584407, 2023). "GOPC-ROS1 was reported as the most common ROS1 alteration in glioma." (PMID 33673070, 2021). "Concerning the expression of ROS1 in gliomas, the results were contradictory." (PMID 28960893, 2017). "Therefore, glioma cases with cytosolic ROS1 fusions could be proposed to possess greater opportunities to be given appropriate chemotherapy other than the current standard treatment using the alkylating agent temozolomide." (PMID 38201436, 2023). "Thus, ROS1-circENTPD7 feedback contributes to glioma pathogenesis." (PMID 32308563, 2020). "Occurring in newborns and infants, these glial tumors are characterized by a distinct molecular profile driven by kinase fusion genes involving the NTRK family, ALK, ROS1 or MET." (PMID 38902810, 2024). "Infant-type hemispheric glioma is commonly initiated by a fusion event involving a receptor tyrosine kinase (RTK) gene, such as NTRK1/2/3, ALK, ROS1, or MET." (PMID 39273062, 2024). "These include “diffuse midline gliomas (H3 K27-altered)”, “diffuse hemispheric gliomas (H3 G34-mutant)”, “diffuse pediatric-type high-grade gliomas (H3-wildtype and IDH-wildtype)” and “infant type hemispheric gliomas (ALK, MET, NTRK 1/2/3 or ROS1 fusion)”." (PMID 38525424, 2024). "Tumors harboring NTRK, ALK, ROS1 and MET fusions have been classified in WHO CNS 5 under the umbrella term infant-type hemispheric gliomas due to their hemispheric predominance (96.7% of fusions)." (PMID 38525424, 2024). "Fusions with receptor tyrosine kinase genes (such as ALK, ROS1, NTRK, and MET) are highly prevalent and preclinical studies show promising results for kinase inhibitors for this glioma type." (PMID 39273062, 2024). "In this regard, entrectinib, an inhibitior against TRKA/B/C and ROS1 and ALK, was developed as a therapeutic target for pediatric refractory gliomas." (PMID 37372381, 2023). "Combination treatment with the chemotherapeutic agent temozolomide and an inhibitor of ROS1, JAK2, or a downstream target of STAT3, demonstrated antitumor effects against KLC1-ROS1 fusion-expressing glioma cells." (PMID 38201436, 2023). "Additional less frequently reported alterations were detected in infiltrating gliomas including an NTRK2-ETV6 fusion (1 IDH-mutant astrocytoma) and ROS1-GOPC fusions (2 in IDH-wildtype infiltrating astrocytomas)." (PMID 36397144, 2022). "NTRK1-3, ROS1, and ALK fusion genes in infantile glioma are targetable, therefore, nationwide adaptation of NGS to evaluate these fusion genes and more extensive accumulation of clinical data are required." (PMID 33673070, 2021). "Importantly, in pediatric gliomas, gene fusions involving anaplastic lymphoma kinase (ALK), ROS proto-oncogene 1 (ROS1), neurotrophic tyrosine receptor kinase (NTRK2) and MET define a distinct, hemispheric high-grade subgroup with intermediate prognosis." (PMID 41514664, 2026). "In glioma, the fusion of KLC1 with ROS1 activates the JAK-STAT pathway." (PMID 38923999, 2024).
glioma (continued). "DNA methylation analyses of a large case series revealed that ROS1-fused tumors clustered into different glioma groups, suggesting that ROS1 fusions are not specific to a single glioma type." (PMID 39409964, 2024). "Here, we investigated the detailed molecular oncogenic mechanisms of a novel receptor tyrosine kinase (RTK) fusion, KLC1-ROS1, with an adapter molecule, KLC1, and an RTK, ROS1, discovered in pediatric glioma, and we explored a novel therapeutic target for glioma that possesses oncogenic RTK fusion." (PMID 38201436, 2023). "When wild-type ROS1 and KLC1-ROS1 fusions were stably expressed in the human glioma cell lines A172 and U343MG, immunoblotting revealed that KLC1-ROS1 fusion specifically activated the JAK2-STAT3 pathway, a major RTK downstream signaling pathway, when compared with wild-type ROS1." (PMID 38201436, 2023). "Additionally, the classification now recognizes infant-type hemispheric glioma as a separate high-grade glioma category characterized by a unique molecular profile, including fusion genes involving ALK, ROS1, NTRK1/2/3, or MET, predominantly seen in newborns and infants." (PMID 38137148, 2023).
breast carcinoma (37 papers, 2013 to 2025). "Ilirjana Bajrami and colleagues’ study unveiled a remarkable discovery, revealing synthetic lethality between the inhibition of ROS proto-oncogene 1 (ROS1) and the E-cadherin-deficient breast cancer subtype." (PMID 38273343, 2024). "CDH1-mutated breast cancer cells are sensitive to ROS1 tyrosine kinase inhibitors including foretinib or crizotinib." (PMID 33004031, 2020). "We identified germline pathogenic variants in familial breast cancer patients in ROS1 and RASAL1 genes." (PMID 32906649, 2020). "The aberrant expression of ROS1 is implicated in a variety of cancers including lung cancer and breast cancers." (PMID 30791612, 2019). "This is the first study to show that activation of the ROS1 protein by alcohol exposure in breast cancer cells is associated with the MAPK pathway." (PMID 23292247, 2013). "Therefore, ROS1 inhibitors may be of benefit for patients with CDH1 mutated breast cancers, in combination with PI3K or AKT inhibitors, with or without immunotherapy, and warrant further investigation in early clinical trials." (PMID 32983983, 2020). "The results revealed a correlation between elevated levels of FAK or ROS1 expression and reduced OS in breast cancer patients." (PMID 38273343, 2024). "Our study unveiled elevated FAK and ROS1 levels in breast cancer tissue compared to normal breast tissue." (PMID 38273343, 2024). "According to the TIMER database, the levels of FAK and ROS1 were higher in breast cancer tissue in comparison to normal breast tissue." (PMID 38273343, 2024). "Initially observed in glioblastoma multiforme, ROS1 rearrangements have since been identified in numerous cancer types, including cholangiocarcinoma, gastric cancer, ovarian cancer, and breast cancer." (PMID 38273343, 2024). "ROS1+ breast cancer is the third most common ROS1 fusion constituting 2.7% of the ROS1+ solid tumors." (PMID 37853341, 2023). "Although the hormonal status of these patients were not described in the paper, a prior case report on inflammatory breast cancer harboring CD74-ROS1 was triple negative and so were 3 out of 7 cases of ROS1+ breast cancer in our study." (PMID 37853341, 2023). "The median TMB was 4 mutations/MB for all ROS1+ tumors (n = 259) while it was 4 in NSCLC, 3 in GBM and 5 in breast cancer patients with ROS1 fusions." (PMID 37853341, 2023). "In vivo, inhibition of ROS1 has been shown to produce significant antitumor effects in different models of E-cadherin-defective breast cancer." (PMID 32983983, 2020). "The role of ROS1 gene in growth/survival and chemo-sensitization of breast cancer cells (MCF-7 and 4T1) was validated through intracellular delivery of ROS1 siRNA after being embedded into these nanoparticles." (PMID 29932151, 2018). "Moreover, the miR-33a level is inversely associated with the expression of ADAM9 and ROS1 in breast cancer tissues, indicating that miR-33a may inhibit breast cancer cell proliferation and metastasis, at least in part, by downregulating the levels of ADAM9 and ROS1." (PMID 26507842, 2015). "Taken together, these results indicate that ADAM9 and ROS1 are direct targets of miR-33a in breast cancer cells." (PMID 26507842, 2015). "When T47D human breast cancer cells are exposed to alcohol, the expression of ROS1 is upregulated, and autophosphorylated ROS1, in turn, activates MSK1 via ERK1/2 in the MAPK pathway." (PMID 23292247, 2013). "The ROS1 amplification breast cancers were found to have higher pCR rate (p = 0.049)." (PMID 32638235, 2020). "Based on our results and previous studies, it is believed that breast cancer cells exposed to alcohol show increased cancer cell growth by activating the MAPK pathway through ROS1 protein, therefore confirming that alcohol consumption is detrimental to breast cancer patients." (PMID 23292247, 2013). "To investigate the clinical significance between FAK and ROS1 in TNBC, we conducted a comprehensive survey of mRNA levels in breast cancer and normal breast tissue." (PMID 38273343, 2024).
breast carcinoma (continued). "Certain targets were enriched in specific cancer types as expected based on the clinical treatment landscape or tumor biology (eg, EGFR, MET, ROS1, MET, and ALK in NSCLC; or ERBB2, CDK4, CDK6, aromatase, and ER in breast cancer)." (PMID 37682776, 2024). "The frequency of ROS1 fusion was approximately 0.47% among NSCLC, 0.29% for GBM, 0.04% of breast cancer." (PMID 37853341, 2023). "Further study showed that miR-33a overexpression inhibited metastatic breast cancer cell growth and mobility in vitro and in vivo by targeting ADAM9 and ROS1." (PMID 32206036, 2020). "Immunohistochemical staining showed that breast cancer tissues with high miR-33a expression have low expression of ADAM9 and ROS1, whereas breast cancer tissues with low miR-33a expression exhibit high expression of ADAM9 and ROS1." (PMID 26507842, 2015). "In breast cancers, the most prevalent fusion genes were FGFR family genes (total, 0.48%; FGFR2, 0.34%; FGFR1, 0.14%), ErbB family genes (total, 0.47%; EGFR, 0.20%; ERBB2, 0.27%), ALK (0.27%) and ROS1 (0.07%)." (PMID 36369474, 2022). "MiR-33a might inhibit breast cancer cell proliferation and metastasis by suppressing ADAM9 and ROS1." (PMID 26507842, 2015). "Thus, silencing overexpressed ROS1 and EGFR could be a promising modality for breast cancer treatment." (PMID 30791612, 2019). "However, the successful approval of TKIs to treat ROS1-, RET-, NTRK1-, PDGFR-α, and AXL-rearranged NSCLC is vitally important as it sets the example for approval of TKIs to treat the same RTK-rearranged common epithelial tumors such as colon, gastric, and breast cancers." (PMID 24744988, 2014). "Napsin A and ROS1 could also be positive in ~90% and 2% of NSCLC cases, respectively, while they are typically negative in primary breast cancer." (PMID 40134856, 2025).
squamous cell carcinoma (32 papers, 2015 to 2025). A carcinoma arising from squamous epithelial cells. "Detection of sensitive mutations in genes, such as EGFR, ALK, and ROS1, is required for advanced non-squamous cell carcinoma of NSCLC." (PMID 35029237, 2022). "Partial genomic profiling (PCR EGFR and/or FISH/IHC ALK and/or ROS1) was obtained in an additional 23 cases (24%), seven of which were squamous cell carcinomas where EGFR status alone was considered sufficient for treatment decision." (PMID 35108331, 2022). "In the case of adenocarcinoma (even in dimorphic combination with squamous cell carcinoma), a molecular genetic assay of EGFR mutations (18–21 exons), BRAF, V600E, ALK, and ROS1 is recommended." (PMID 35982978, 2022). "In squamous cell carcinoma cases, genetic abnormalities are rare, and the therapy response of ROS1-fusion positive cases with squamous cell carcinoma still need further study." (PMID 25905642, 2015). "ROS1 fusions were detected in 2.6% of non-squamous and 1.9% of squamous carcinomas, while BRAF V600E mutations were found in 3.7% and 1.9%, respectively." (PMID 41465119, 2025). "Furthermore, other important genes related to cancer treatment including CSMD1 (potential suppressor of squamous cell carcinomas), BRIC6 (apoptosis-associated gene), and ROS1 (the member of tyrosine kinase insulin receptor genes) were more enriched in this study." (PMID 34368001, 2021). "However, Davies’s group reported 2 of 428 cases with ROS1 rearrangement in squamous carcinoma." (PMID 25905642, 2015). "All included patients were ROS1 fusion NSCLC, with 77 presenting with adenocarcinoma, 3 with squamous cell carcinoma, and 2 with adenosquamous carcinomas." (PMID 38835380, 2024). "They recommend systematic biomarker/molecular testing including PDL1, EGFR, ALK, ROS1, and BRAF for all non-squamous cell carcinomas." (PMID 33704175, 2020). "The absence of ALK and ROS1 rearrangements in squamous cell carcinoma suggests a lesser role for these fusions in that subtype." (PMID 40502411, 2025). "All ALK- and ROS1-positive cases were found in adenocarcinoma patients, and no ALK or ROS1 fusions were detected in patients with squamous cell carcinoma." (PMID 39685930, 2024). "No ROS1 rearrangement was identified with squamous cell carcinoma in our cohort." (PMID 25905642, 2015). "In stage IV, molecular profiling (gene testing for EGFR, ALK, ROS1 and BRAF) was performed in 94.3% of patients with adenocarcinoma, non-specific carcinoma, or nonsmoking squamous cell carcinoma." (PMID 39147937, 2025). "The availability of specific inhibitors of ROS1 and their clinical benefit should lead to simultaneous testing of ROS1 rearrangement with other recurrent biomarkers in NSCLC (e.g EGFR and ALK) in all advanced stage never/light smokers with squamous cell carcinoma and non-squamous NSCLC." (PMID 35303812, 2022). "ROS1 rearrangement should be tested in patients with advanced stage (IIIB-IV) non-squamous NSCLC, regardless of its clinical characteristics and should not be tested in squamous cell carcinoma (except in the context of patients with no or low tobacco exposure and younger than 50 years)." (PMID 35303812, 2022).